CD44 (CD44 molecule (IN blood group))
Diseases named in the same sentence as CD44 in open-access papers (continued):
Sharing a sentence is not in itself a finding about the gene and the disease.
cancer (continued). "Cancer stem cell (CSC) markers, including CD133 and CD44, characterize the CSC phenotype associated with tumor initiation, treatment resistance, and cancer recurrence." (PMID 40868292, 2025). "ARF6 has been associated with several cell-surface receptors expressed on cancer cells, such as CD147, CD44, CD98, CD55, and CD59." (PMID 40733075, 2025). "CD44 is a type I transmembrane glycoprotein that is expressed in the cancer cell surface membrane and is essential for cellular adhesion, migration, and proliferation." (PMID 40738059, 2025). "This ligand promotes receptor-mediated endocytosis, which guarantees selective absorption by cancer cells that express CD44." (PMID 41367861, 2025). "Both treatment doses elevated the Bax/Bcl-2 ratio and reduced the expression of cancer stem cell markers CD44, EpCam, and VEGF compared to controls." (PMID 40371330, 2025). "CD44 functions as an indicator of cancer stem cells and governs epigenetic plasticity by facilitating iron endocytosis." (PMID 41210681, 2025). "This review primarily discusses the molecular mechanisms of ESRP1 in regulating cancer metastasis, particularly its regulatory effects on CD44 splicing and the EMT process." (PMID 40046628, 2025). "These cancer-related phosphoproteins were enriched in pathways, including translation initiation (such as EIF4EBP1_T70 and EIF5B_S214), cell migration (such as CD44_S183 and ITGB4_S1387), and cell proliferation (such as STAT4_S715 and TP53BP1_S403)." (PMID 40917497, 2025). "In summary, this work introduces a sEVs isolation method and sheds light on the role of HA MW in enhancing cellular uptake of CD44 overexpressing cancer cells." (PMID 40468893, 2025). "A 2023 study reported the presence of SPP1-expressing TAM in alpha-fetoprotein-positive HCC tissues and demonstrated that SPP1 can inhibit the anti-cancer activity of T cells by binding to CD44." (PMID 38757323, 2025). "CD44 has a crucial role in controlling many important signaling pathways that regulate cancer invasion, metastasis, and resistance to treatment." (PMID 41367861, 2025). "This pattern coincided with the upregulation of key markers associated with cancer stemness (CD133, CD44) and metastasis/invasion (MMP7, CD74), highlighting FXYD5 as a potential driver of malignant progression." (PMID 41457101, 2025). "Mechanistically, the reduction of TIP60 resulted in a decrease in CD44 expression, a critical marker for cancer stem cells (CSCs)." (PMID 40422189, 2025). "Surviving MCF-7 cancer cells further showed high CD44 and low CD24 gene expression, a cancer stem cell phenotype that has been described to be promoted by polyclonal allogenic T cells." (PMID 40240529, 2025). "The system also enriched cancer stem-like properties, with higher expression of stemness-associated genes (CD24, CD44, CD133, ALDHA1, CXCR4, Sox2, Oct4, Nanog, and KLF4) and expansion of CSC populations expressing (CD44, CD90, CD117, EpCAM, and CK19)." (PMID 41149589, 2025). "The polymer itself allows for functional modifications, such as the connection to hyaluronic acid, which improves PDT selectivity for CD44-overexpressing cancer cells." (PMID 41374877, 2025). "The phenotype analysis of cells isolated and expanded from OSCC tissue samples provided heterogeneous results for putative cancer stem cell markers (CD44, CD133 and CD166) expression." (PMID 41303421, 2025). "CD44, the primary cell adhesion receptor expressed in cancer stem cells (CSC), has a specific extracellular domain in the N-terminal region that binds HA in the ECM; this domain is called the HA-binding domain, as shown in the Graphical abstract." (PMID 41440277, 2025). "Scientists have long studied proteins on the surface of cancer cells, called CD44, as potential clues, but their role has been unclear." (PMID 41514534, 2025). "We also observed that the presence of 1% HA-DPPE allowed the nanocarriers to be actively targeted towards CD44-overexpressing cancer cells." (PMID 40142123, 2025).
cancer (continued). "In contrast, our work here reports spheroids that distinctively demonstrate cellular heterogeneity as evidenced by the emergence of a CD44+ CD133+ drug‐resistant niche at the periphery of the cancer spheroids." (PMID 40569213, 2025). "Another study also proved that 5FU resistant cancer cells show an upregulation of CSC marker proteins like CD44, OCT4 and NANOG." (PMID 40045186, 2025). "These cell lines showed the presence of cancer stem cell (CSCs) population, i.e., the ALDHbr/CD44+ population." (PMID 40394426, 2025). "NINJ2 O/E in cancer cells increased the CD44+ cancer stem cell population and induced cell cycle arrest." (PMID 40518514, 2025). "CD44-targeted nanocarriers can manipulate these pathways, interrupting the complex cellular processes that play a role in the advancement of cancer." (PMID 41367861, 2025). "Despite the relatively smaller number of cells in the ‘CD44_high’ cluster, CD44 expression, along with other cancer stem cell marker genes such as LGR5, ALDH1A1, and FUT4, was significantly higher compared to the ‘CD44_low’ cluster." (PMID 40849307, 2025). "This connection promotes specific attachment and uptake of the nanocarriers into cancer cells that express CD44, allowing for precise delivery of drugs." (PMID 41367861, 2025). "With its expression in a wide variety, CD44 has also become the most common surface biomarker of cancer stem cells." (PMID 41155181, 2025). "Common markers include EpCAM, used for epithelial cancers; CD44 and CD24, which are associated with cancer stem cells; and cytokeratins, such as CK8 and CK18." (PMID 40260304, 2025). "The mechanism through which CD44 forms complexes at the cellular membrane with additional receptors is quite often utilized by cancer cells and seems to be successful in the promotion of cell death resistance." (PMID 40114966, 2025). "The CD44; cancer stem cell markers are involved in cell-cell interactions, cell adhesion, and migration and are often found upregulated in CTCs." (PMID 40260304, 2025). "As a marker of cancer stem cells (CSCs), CD44 facilitates the formation of invadopodia, specialized structures that enable ECM degradation and tissue penetration." (PMID 41009438, 2025). "Considering all of this evidence, it is evident that nanoparticles specifically designed to target CD44 can greatly enhance the transportation of therapeutic medications to cancer cells." (PMID 41367861, 2025). "The expression of specific CD44 isoforms is correlated with the corresponding cancer type (see Supplementary document for a more detailed discussion)." (PMID 41440277, 2025). "FKBPL-based therapeutic peptide mimetic, AD-01 (preclinical peptide candidate), has showed a potent anti-angiogenic and anti-cancer stem cell effects in cancer via CD44 and DLL4." (PMID 40109359, 2025). "The use of ELISA-based methods for the quantification of proteins specific to cancer-derived exosomes, such as CD44, CD44v6, CD9, EpCAM, and CD81, has been well-documented." (PMID 41573685, 2025). "All spheroids and tumoroids generated with OVCAR8 maintained a high baseline fraction of CD44 positive cancer cells (e.g., 99.7±0.07% for OVCAR8-only spheroids)." (PMID 40585272, 2025). "Our study included an investigation of the cell surface markers CD44, CD133, and CD166 associated with cancer ‘stemness’, the presence of which was observed in patients with cancer of the oral cavity." (PMID 41303421, 2025). "Hyaluronic acid (HA) can bind to the cell membrane glycoprotein cluster of differentiation 44 (CD44), which is considered a cancer stemness marker, thereby transducing intracellular signaling and regulating a variety of biological activities of cancer cells." (PMID 41451369, 2025). "In docetaxel-resistant TNBC cells, KIF11 knockdown inhibited the proliferation of CD44+/CD24-cancer stem-like cells and removed their self-renewal capacity." (PMID 41487287, 2025).
cancer (continued). "CD44, a cell surface glycoprotein involved in cell−cell interactions, is overexpressed in many cancers such as pancreatic, breast, ovarian, brain and lung cancers, compared to normal cells." (PMID 40867257, 2025). "Even though preclinical research data suggest that total CD44 play a significant role in the chemoresistance of cancer patients, there is a limited amount of conducted clinical studies regarding total CD44 targeted therapies." (PMID 40114966, 2025). "When we blocked CD44-HA binding with a polyclonal antibody, cancer cell migration was significantly delayed, showing that strong CD44-HA binding is important for cancer cell migration." (PMID 40881990, 2025). "Our results showed that ALDH1, CD44, Sox2, Olig2, BMI1, LGR4, LGR5, Integrin α6, L1CAM, and ABC transporter associated with cancer stem cells were significantly downregulated." (PMID 39721005, 2025). "CD44 primarily influences cancers by activating signaling pathways that are crucial for apoptosis, epithelial-mesenchymal transition (EMT), and drug resistance." (PMID 41367861, 2025). "A novel form of metformin called Metformin-butyrate (MFB) has shown enhanced efficacy in specifically attacking the CD44+/high/CD24−/low cancer stem cell-like group in breast cancer and blocking the growth of mammospheres in contrast to regular metformin." (PMID 40497987, 2025). "In our previous investigations, we have successfully isolated and characterized CD44+ cells in which the expression of embryonic/cancer stem cell markers OCT4, SOX2, and NANOG was significantly higher than in the CD44− cell populations." (PMID 39941011, 2025). "This study evaluated the expression of putative cancer stem cell markers—CD44, CD133, and CD166—in OSCC tissues and explored their associations with clinical parameters, including salivary flow rates." (PMID 41303421, 2025). "In contrast, RHBDL2 has been shown to delay cancer progression, with its upregulation being required for the spontaneous conversion of CD44−/CD24− breast cancer cells into CD44+/CD24− cancer stem cells in patient‐derived samples." (PMID 41015904, 2025). "Briefly, PDAC-secreted AREG stimulates the production of CCL5 from macrophages, which confers stemness and chemoresistance to cancer cells through the CCR5/AKT/Sp1/CD44 axis." (PMID 39814914, 2025). "In summary, these findings suggest that cancer-derived YAP activity contributes to the HAS2/HA/CD44 interaction between CAFs and TAMs and the enhanced interaction of PD-L1 and PD-1 between TAMs and T cells." (PMID 39946200, 2025). "CD44 expression in cancer is regulated by multiple mechanisms, including transcriptional, post-transcriptional, and epigenetic changes." (PMID 40363706, 2025). "These HA-based nanomaterials for DOX delivery can selectively target CD44-overexpressing cancer cells, and they enable the internalization of DOX into targeted cells via a receptor-mediated pathway, leading to enhanced antitumor activity." (PMID 39997114, 2025). "Despite these discouraging examples, a clinical trial testing a Notch signaling pathway inhibitor in BCSCs successfully reduced ALDH+ cells, along with other cancer stem cell markers such as CD44/CD24 and mammosphere-forming efficiency." (PMID 40869256, 2025). "The primary cell surface receptor for HA is CD44, and CD44-HA interactions have been shown to be important in determining cancer cell behaviour in vitro." (PMID 40881990, 2025). "Protein expression analysis showed that im.CTCs express CD45 as well as other immune-related markers, such as CD3 and CD4, and the cancer stemness marker, CD44." (PMID 40707771, 2025). "In the late 1990s, CD44 protein was considered one of the most promising candidate biomarkers for early cancer diagnosis." (PMID 41440277, 2025). "Inadvertently, these results demonstrated that spheroid confinement from the hydrogel cups was responsible for the emergence of a drug‐resistant CD44+ CD133+ cancer cell population." (PMID 40569213, 2025).
cancer (continued). "Our previous studies demonstrated that cancer cell-derived extracellular vesicles (EVs) and their surface proteins CD44 and CD81 contribute to the modulation of the microenvironment and EV-recipient cells." (PMID 40818975, 2025). "Although caffeic acid had a minor effect on cancer cell viability, it reduced the expression of CD44, EpCAM, and/or ALDH1, as well as OCT4, BMI-1, and Lin-28B, in TNBC cells." (PMID 40687439, 2025). "The activation of the Wnt/β-catenin pathway by CagA+ H. pylori in cancer cells promotes the expression of key cancer stem cell markers, which encompass CD44, Lgr5, Oct4, Nanog, and c-myc." (PMID 40497987, 2025). "CD44 is a cancer stem cell marker and has a cell-adhesive capacity for interaction with cancer cells." (PMID 39946200, 2025). "Beyond supporting BC cell migration and metastasis, CD44 is a known marker and promoter of cancer cells stemness." (PMID 40221767, 2025). "Further research indicates the interaction between SPP1 and CD44 is a key mechanism in maintaining cancer stem cell characteristics and enhancing chemotherapy resistance." (PMID 41391064, 2025). "During EMT, cancer cells, often expressing elevated CD44, acquire stem cell-like properties and exhibit increased invasiveness." (PMID 40221767, 2025). "Previous studies have demonstrated the role of IL-6 signaling in promoting CD44 expression and its importance in conferring cancer stem cell properties." (PMID 40430044, 2025). "In fact, PP-HA-BSA-NPs effectively targeted these cancer cell lines expressing CD44 while retaining the high anticancer activity of the free drug, allowed a minimum loading of 10-fold the IC50 value, and showed an exceptional safety profile." (PMID 41002533, 2025). "CD44 is a multifunctional cell surface adhesion receptor highly expressed in many cancers, promoting migration and invasion processes involved in metastasis." (PMID 40806166, 2025). "To determine how a fibrotic TME plays a role in steatotic liver–associated liver metastasis, we studied an ECM component, HA, a signaling molecule that activates cancer-promoting pathways, including CD44." (PMID 39946200, 2025). "Accordingly, the generation and characterization of monoclonal antibodies (mAbs) that recognize each variant exon are essential for elucidating their distinct biological functions and for the development of CD44-targeted cancer therapies." (PMID 41009730, 2025). "CD44 is a cell adhesion molecule that promotes cancer cell proliferation and metastasis by upregulating TGF-β expression." (PMID 40943648, 2025). "One noble example is CD44, a multifaceted glycoprotein on the cell surface that can undergo splicing to produce various isoforms, directly influencing cancer progression and drug resistance." (PMID 40538061, 2025). "Compared to controls, radiation, smoke, and RS increased the frequency of CD44-expressing cancer cells 1.05-, 1.08-, and 1.09-fold, respectively." (PMID 40282522, 2025). "CD44, a well-recognized cancer stem cell marker, contributes to epithelial–mesenchymal transition (EMT) by enhancing cellular plasticity, migration, and invasion through its interactions with hyaluronan and the regulation of key EMT transcription factors." (PMID 41266827, 2025). "Adhesion to the endothelium through CD44 has been shown to involve VCAM-1, a transmembrane glycoprotein implicated in cancer progression and metastatic dissemination in several malignancies, including breast cancer." (PMID 40890143, 2025). "Overall, our findings reveal the striking potential of sTN58 as a targeting reagent for the recognition and therapy of cancers overexpressing CD44." (PMID 40342488, 2025). "Folate receptors can facilitate selective drug delivery by binding to cancer cells, while CD44 is a cell-surface glycoprotein involved in cell–cell interactions." (PMID 41011159, 2025). "Curcumin, a polyphenol derived from turmeric, has also been shown to decrease the expression of CD44, a key marker of cancer stem cells." (PMID 40443562, 2025).
cancer (continued). "Cytoplasmic PKM2 interacts with CD44 (a cell surface biomarker of cancer stem cells) and boosts glucose uptake and PPP flux, which maintains cellular redox homeostasis and protects cancer cells against anticancer drugs." (PMID 40612109, 2025). "The topmost expressed epitopes in ascitic fluid EVs were CD326/EpCAM, CD133/1, HLA-DR, CD24 and CD44, which are cancer-related markers." (PMID 40259212, 2025). "Flow cytometry revealed significant increases in cancer stem-like cell (CSC) markers CD44 and CD90 in the tri-component tumoroids." (PMID 40585272, 2025). "Evidence supporting resveratrol's potential to suppress CD44 and inhibit metastasis has gained significant attention in cancer therapy research." (PMID 40888184, 2025). "Treatment with the MELK inhibitor OTSSP167 significantly reduced mammosphere formation efficiency in cancer stem cell populations (CD44+/CD24− and ALDH+) compared to untreated controls." (PMID 40076867, 2025). "The development of CD44 aptamers that specifically target CD44 can be utilized to target CD44-positive cells, including cancer stem cells, and for drug delivery." (PMID 40001633, 2025). "Lastly, total CD44 was shown to promote autophagy and chemoresistance in several cancers through OPN-CD44-ITG-p38MAPK and OPN-CD44-NF-κB signaling." (PMID 40114966, 2025). "CD44 is also a molecular marker for cancer stem cells (CSCs) and has been found to play a role in the EMT process." (PMID 39815326, 2025). "Significantly higher levels of GFP were detected in human CD44+ cancer cells injected with αEGFR‐tLNPs compared to naked or iso‐tLNPs." (PMID 39736115, 2025). "Our analysis identified E2F4 and TFDP1, two core components of the DREAM transcriptional repression complex, as transcriptional modulators preferentially activated by irinotecan in EPCAM+/CD44+/CD166+ as compared to EPCAM+/CD44neg/CD166neg cancer cells." (PMID 39896677, 2025). "Cancer stem cell-related markers, CD44, ABCG2, BMI1, and KRT19, expression in subclusters from trajectory, indicated enhanced self-renewal capacity in SRGN-high malignant cells." (PMID 40384866, 2025). "CD44 is a prominent surface marker on CSCs and a promising therapeutic target across various cancers due to its role in cell-to-cell interactions, cell-to-matrix interactions, and activation of different signaling pathways." (PMID 40291275, 2025). "The soluble form of CD44 has been identified as a cancer biomarker in biological fluids, including serum, saliva, urine, ascitic fluid, and pleural fluid." (PMID 41440277, 2025). "Human CD44 consists of 19 exons locating on chromosome 11p13, and serves as a biomarker for cancers." (PMID 39815331, 2025). "Our single-cell analysis revealed that steatotic liver promoted CD44 and PD-L1 expression in M2-TAM and cancer cells, which was associated with the nearest CAF distance and density." (PMID 39946200, 2025). "CD133 and CD44 are specific markers of stem cell-like properties in various cancer types; they have been widely studied in PCa." (PMID 40735647, 2025). "Further analyses verified that macrophages mainly interacted with fibroblasts via MIF-ACKR3 and HBEGF-EGFR, and exhibited enhanced interactions with epithelial and cancer cells through MIF-(CD74 + CD44)." (PMID 41150752, 2025). "CD44–HA interactions activate cellular signaling pathways that promote cancer cell proliferation, invasion, and metastasis." (PMID 41440277, 2025). "Our findings highlight X-aptamers’ potential in targeting CD44-positive cancer cells, including cancer stem cells, which are often resistant to conventional therapies." (PMID 40001633, 2025). "In vitro studies revealed that HA/DOX nanoaggregates effectively targeted CD44-overexpressing cancer cells, selectively delivering DOX into the cell nuclei more efficiently than free DOX and resulting in enhanced cytotoxic effects." (PMID 39997114, 2025). "Flow cytometry was used for CD44/CD133 cancer stem cells markers analysis, and genes expression were quantified using qPCR." (PMID 41154846, 2025).